PRR23E (PRR23 family member E)
Synonyms: C3orf56; FLJ40141
Tractability: No criterion of Open Targets' tractability assessment is met for any kind of drug.
Gene: Protein-coding gene on chromosome 3 (127,193,131 to 127,198,185, forward strand). Ensembl gene ENSG00000214324.
Subcellular location (Human Protein Atlas): Nucleoplasm; Centrosome; Cytosol
Gene Ontology:
Molecular function: protein binding
Genetic constraint (gnomAD): Loss-of-function variants: 1 observed, 0.32 expected, observed/expected ratio (o/e) 3.13. That is too few expected variants to judge how well the gene tolerates losing a copy. Missense variants: 339 observed, 316.27 expected, observed/expected ratio (o/e) 1.07, 90% interval 0.98 to 1.17. Synonymous variants: 125 observed, 124.25 expected, observed/expected ratio (o/e) 1.01, 90% interval 0.87 to 1.17.
Homologues: Orthologues: chimpanzee PRR23E (98% identical). Paralogues in human: PRR23B (21% identical), PRR23A (19% identical), PRR23C (19% identical), PRR23D1 (14% identical), PRR23D2 (14% identical).